FEZ2 (fasciculation and elongation protein zeta 2)
Description:
Involved in axonal outgrowth and fasciculation.
Synonyms: HUM3CL
Tractability: PROTAC: ubiquitination databases record sites on it.
Gene: Protein-coding gene on chromosome 2 (36,531,805 to 36,646,087, reverse strand). Ensembl gene ENSG00000171055.
Subcellular location (Human Protein Atlas): Nucleoli; Nucleoli rim; Cytosol; Golgi apparatus
Gene Ontology:
Molecular function: protein binding
Biological process: negative regulation of autophagosome assembly; axon guidance; nervous system development; signal transduction
Cellular component: axon; cytoplasm
Genetic constraint (gnomAD): Loss-of-function variants: 29 observed, 19.51 expected, observed/expected ratio (o/e) 1.49, 90% interval 1.1 to 1.9. The synonymous counts are far from expectation, so gnomAD's model fits this gene poorly and the ratio says little. Missense variants: 416 observed, 251.78 expected, observed/expected ratio (o/e) 1.65, 90% interval 1.52 to 1.79. Synonymous variants: 162 observed, 101.32 expected, observed/expected ratio (o/e) 1.6, 90% interval 1.41 to 1.82.
Homologues: Orthologues: chimpanzee FEZ2 (98% identical), macaque FEZ2 (98% identical), dog FEZ2 (95% identical), pig FEZ2 (94% identical), rabbit FEZ2 (93% identical), rat Fez2 (90% identical), mouse Fez2 (89% identical), guinea pig FEZ2 (77% identical), tropical clawed frog fez2 (71% identical), Drosophila melanogaster Unc-76 (35% identical), Caenorhabditis elegans unc-76 (31% identical). Paralogues in human: FEZ1 (47% identical).
Diseases named in the same sentence as FEZ2 in open-access papers:
FEZ2 is named in the same sentence as 8 diseases in open-access papers, as found by Europe PMC text mining. Sharing a sentence is not in itself a finding about the gene and the disease. The quoted sentences say what the papers report.
osteoarthritis (1 paper, 2024). A noninflammatory degenerative joint disease occurring chiefly in older persons, characterized by degeneration of the articular cartilage, hypertrophy of bone at the margins and changes in the synovial membrane. "Exosomes of miR-429 derived from adipose-derived stem cells (ADSCs) improve cartilage damage in osteoarthritis via autophagy by targeting FEZ2." (PMID 38767703, 2024).
ovarian carcinoma (1 paper, 2022). A malignant neoplasm originating from the surface ovarian epithelium. "Interestingly, two candidate genes (SEC22B and FEZ2), which were highly associated with ovarian cancer in three cancer databases, were identified in the term “selective autophagy”." (PMID 35038288, 2022).
pancreatic cancer (1 paper, 2022). "To further validate the expression pattern of FEZ2 in pancreatic cancer, we compared 178 PDAC tissues from TCGA database with 165 normal pancreas tissues from GTEx database." (PMID 35036176, 2022). "Taken together, these data demonstrated the upregulation of FEZ2 in pancreatic cancer." (PMID 35036176, 2022). "However, as a highly conserved gene in eukaryotes, the role of Fasciculation and Elongation protein Zeta 2 (FEZ2) in pancreatic cancer progression is not clear." (PMID 35036176, 2022).
cancer (3 papers, 2022 to 2024). A tumor composed of atypical neoplastic, often pleomorphic cells that invade other tissues. "Taken together, FEZ2 expression was positively correlated with immune cell infiltration, and increasing of cancer associated fibroblast infiltration might be a reason for chemotherapy resistance." (PMID 35036176, 2022). "Also, we found that FEZ2 was positively related to cancer associated fibroblast." (PMID 35036176, 2022). "Since there is no study reported that FEZ family play an oncogenic role in any type of cancer previously, this led us to examine the function of FEZ2 in PDAC." (PMID 35036176, 2022). "To investigate the expression pattern of FEZ family in different cancer types, we searched Oncomine online website and found FEZ1 and FEZ2 were both upregulated in different cancer types." (PMID 35036176, 2022). "Both FEZ1 and FEZ2 showed dysregulation in many cancer types, but only few types of cancer showed an upregulation of FEZ2, which including PDAC." (PMID 35036176, 2022). "By mining of The Cancer Genome Atlas (TCGA) database, we found that FEZ2 was upregulated in PDAC tissues and FEZ2 expression was negatively regulated by its methylation." (PMID 35036176, 2022). "Although the Wnt signaling pathway was involved in many cancer progressions, its function in PDAC and the role of FEZ2 within this pathway need to be studied further." (PMID 35036176, 2022). "Although FEZ2 is dysregulated in some types of cancers, there is no research mentioned that FEZ2 functions as an oncogene or tumor suppressor gene in PDAC." (PMID 35036176, 2022).
tumor (2 papers, 2022). "The results revealed that FEZ2 and miR-433 was negatively correlated in tumor tissues (n = 45, r = −0.3259, P = 0.03)." (PMID 35036176, 2022). "This meant that high FEZ2 expression might promote tumor progression and chemotherapy resistance after surgery." (PMID 35036176, 2022). "Besides, protein expression analysis by immunohistochemistry from The Human Protein Atlas (THPA) showed FEZ2 was highly expressed in PDAC tumor cells (strong intensity) compared with pancreas cells (moderate intensity)." (PMID 35036176, 2022). "Finally, we validated the function of FEZ2 on tumor cell proliferation, migration and 5-FU resistance by using PDAC cell lines and clinical samples." (PMID 35036176, 2022).
FEZ2 also shares sentences with these, for which no sentence is quoted: pancreatic ductal adenocarcinoma (2 papers); liposarcoma (1); round cell liposarcoma (1).